NPR1 (natriuretic peptide receptor 1)
Description:
Receptor for the atrial natriuretic peptide NPPA/ANP and the brain natriuretic peptide NPPB/BNP which are potent vasoactive hormones playing a key role in cardiovascular homeostasis. Plays an essential role in the regulation of endothelial cell senescence and vascular aging. Upon activation by ANP or BNP, stimulates the production of cyclic guanosine monophosphate (cGMP) that promotes vascular tone and volume homeostasis by activation of protein kinase cGMP-dependent 1/PRKG1 and subsequently PRKAA1, thereby controlling blood pressure and maintaining cardiovascular homeostasis.
Synonyms: ANP-A; GC-A; ANPRA; GUCY2A; ANPa; GUC2A; NPRA
Tractability: Small molecule: a structure with a bound ligand is known; a high-quality ligand is known; it belongs to a druggable protein family. Antibody: its Gene Ontology location is reachable by antibodies, with high confidence; UniProt predicts a signal peptide or a membrane-spanning region; the Human Protein Atlas places it where antibodies can reach. PROTAC: ubiquitination databases record sites on it; a small molecule that binds it is known. Other modalities: an approved drug acts on it.
Target class: Lyase; Enzyme; Guanylate cyclase; Receptor guanylate cyclase
Gene: Protein-coding gene on chromosome 1 (153,677,965 to 153,694,110, forward strand). Ensembl gene ENSG00000169418.
Subcellular location: Membrane
Subcellular location (Human Protein Atlas): Nucleoli; Nucleoplasm; Plasma membrane
Pathways (Reactome):
Muscle contraction: Physiological factors
Gene Ontology:
Molecular function: guanylate cyclase activity; hormone binding; natriuretic peptide receptor activity; peptide hormone binding; G protein-coupled peptide receptor activity; peptide receptor activity; ATP binding; phosphorus-oxygen lyase activity; protein kinase activity
Biological process: cGMP biosynthetic process; receptor guanylyl cyclase signaling pathway; regulation of blood pressure; regulation of vascular permeability; blood vessel diameter maintenance; body fluid secretion; cell surface receptor signaling pathway; negative regulation of angiogenesis; negative regulation of cell growth; positive regulation of renal sodium excretion; positive regulation of urine volume; cyclic nucleotide biosynthetic process; dopamine metabolic process; G protein-coupled receptor signaling pathway; intracellular signal transduction; negative regulation of smooth muscle cell proliferation
Cellular component: receptor complex; plasma membrane; ANPR-A receptor complex; endoplasmic reticulum membrane; membrane; nuclear membrane
Genetic constraint (gnomAD): Loss-of-function variants: 56 observed, 104.27 expected, observed/expected ratio (o/e) 0.54, 90% interval 0.43 to 0.67. The upper end of that interval is the gene's LOEUF score, 0.67, which puts it in group 2 of 6, group 1 being the genes least tolerant of losing a copy. Missense variants: 1,064 observed, 1,268.1 expected, observed/expected ratio (o/e) 0.84, 90% interval 0.8 to 0.88. Synonymous variants: 544 observed, 525.1 expected, observed/expected ratio (o/e) 1.04, 90% interval 0.96 to 1.11.
Homologues: Orthologues: chimpanzee NPR1 (99% identical), macaque NPR1 (99% identical), pig NPR1 (93% identical), rabbit NPR1 (92% identical), mouse Npr1 (91% identical), rat Npr1 (91% identical), guinea pig NPR1 (73% identical), zebrafish npr2 (59% identical), Caenorhabditis elegans gcy-28 (45% identical), Drosophila melanogaster CG31183 (45% identical). Paralogues in human: NPR2 (60% identical), GUCY2F (33% identical), GUCY2D (33% identical), GUCY2C (29% identical), GUCY1A2 (17% identical), GUCY1A1 (16% identical), ADCY2 (16% identical), ADCY4 (16% identical), ADCY8 (16% identical), ADCY7 (16% identical), ADCY5 (15% identical), GUCY1B1 (15% identical), and 5 more.
Diseases named in the same sentence as NPR1 in open-access papers:
NPR1 is named in the same sentence as 105 diseases in open-access papers, as found by Europe PMC text mining. Sharing a sentence is not in itself a finding about the gene and the disease. The quoted sentences say what the papers report.
cardiac hypertrophy (33 papers, 2009 to 2025). "Consistently, the ablation of NPPA or NPR1 (the gene encoding NPR-A) as well as NP genetic variants leading to reduced peptide expression have been associated with cardiac hypertrophy and impaired endothelial cell viability and proliferation." (PMID 36982204, 2023). "Ablation of Npr1 also enhances the expression and activation of transcription factors, NF-κB and activating protein-1 (AP-1), which seem to be associated with cardiac hypertrophy, fibrosis, and extracellular matrix remodeling." (PMID 34489721, 2021). "Both of these transcription factors have been found to be associated with cardiac hypertrophy, fibrosis, and extracellular matrix remodeling in Npr1 gene-disrupted mouse models." (PMID 31416126, 2019). "Our findings suggested that ablation of Npr1 triggered a sustained activation of proinflammatory cytokines gene expression and protein levels associated with exaggerated ventricular remodeling and cardiac hypertrophy leading to CVDs." (PMID 34489721, 2021). "Thus, it is thought that in humans there is a positive association between Nppa, Nppb, and Npr1 gene polymorphisms and high BP, cardiac hypertrophy, and heart failure." (PMID 31416126, 2019). "It has been shown that SNP in human Npr1 significantly decreases the expression of Npr1, suggesting that a single allele mutation may be associated with increased susceptibility to hypertension and cardiac hypertrophy." (PMID 31416126, 2019). "Female mice with Npr1 deletion under consecutive lactation cycles exhibit exaggerated cardiac hypertrophy, fibrosis, and cardiac dysfunction." (PMID 38891063, 2024). "Npr1 null animals show hypertension, ventricular fibrosis and cardiac hypertrophy, while Npr2 mutant animals are affected by dwarfism, due to impaired endochondral ossification, and female infertility." (PMID 37162198, 2023). "Mice with homozygous deletion of Npr1 (Npr1−/−) have shown hypertension, cardiac hypertrophy, and sudden death." (PMID 35794311, 2022). "Ablation of Npr1 activates proinflammatory cytokine gene expression in addition to protein levels involved in cardiac hypertrophy and exaggerated ventricular remodeling, leading to cardiac dysfunction and CHF." (PMID 36683859, 2022). "The sex-dependent effects showed significant differences in cardiac hypertrophy between male and female Npr1−/−, Npr1+/−, and Npr1+/+ mice." (PMID 36232788, 2022). "The conditional inactivation of Npr1 in cardiac myocytes, exhibited mild cardiac hypertrophy; however, ANP levels were markedly increased." (PMID 34489721, 2021). "The biomolecules ANP and BNP are endogenous peptides secreted from the heart and signaling, through NPR-1, to reduce cardiac hypertrophy and ventricular fibrosis." (PMID 34070682, 2021). "Overall, the heart weight (HW) and echocardiographic data of Npr1 gene-knockout mutant mice were accompanied by marked cardiac hypertrophy and ventricular enlargement." (PMID 31416126, 2019). "The deletion mutations in Npr1 gene have been suggested to reduce the receptor activity of NPRA and were considered as a potential genetic factor for hypertension and cardiac hypertrophy in humans." (PMID 31416126, 2019). "Mice with 2, 3, or 4 copies of Npr1 were produced to establish a direct gene-dose-dependent effect of Npr1 on BP, cardiac hypertrophy, and inflammatory responses." (PMID 31416126, 2019). "Selective inactivation of Npr1 by homologous lox/Cre-mediated recombination led to only mild cardiac hypertrophy, but ANP levels were significantly increased." (PMID 31416126, 2019). "Genetic mouse models with disruption of both Nppa and Npr1 genes have provided strong support for the role of this hormone-receptor system in the regulation of blood pressure, cardiac hypertrophy, and other physiological functions." (PMID 25202235, 2014).
cardiac hypertrophy (continued). "Deletion of the major natriuretic receptor for atrial natriuretic peptide and BNP, natriuretic peptide receptor-1 in mice (Npr1−/−), resulted in hypertension, cardiac hypertrophy, congestive heart failure and sudden death at 6 months of age." (PMID 22943504, 2012). "Furthermore, after the genetic knockout of Npr1 gene encoding NPR-A in mice, blood pressure rises, and cardiac hypertrophy develops." (PMID 37056987, 2023). "Mice lacking a functional NPR 1 gene encoding NPR-A exhibit hypertension and marked cardiac hypertrophy with interstitial fibrosis, in association with enhanced activation of pro-inflammatory cytokines, probably via nuclear factor kappa mediated signalling pathway." (PMID 31830996, 2019). "Global deletion of Npr1 also activates the calcineurin–NFAT pathway, and its selective inhibition attenuates cardiac hypertrophy and fibrosis." (PMID 38891063, 2024). "Further, both ACE 1 and AT1R were found to be significantly increased leading to cardiac hypertrophy and fibrosis in Npr1–/– mice, but not Npr1+/+ control mice." (PMID 34489721, 2021). "Gene-disrupted Npr1 mutant mice lacking NPRA showed marked cardiac hypertrophy and chamber dilation disproportionate to their increased BP." (PMID 31416126, 2019). "Npr1 gene-knockout mice develop cardiac hypertrophy, fibrosis, and inflammatory responses independent of BP." (PMID 31416126, 2019). "Although both receptors protect from cardiac hypertrophy, their effects on contractility are markedly different, from little effect (NPR1) to pronounced negative inotropic and positive lusitropic responses (NPR2) with unclear underlying mechanisms." (PMID 29934640, 2018). "Furthermore, transgenic mice with the NRP1 gene deletion targeted specifically to cardiac tissue exhibited cardiac hypertrophy in the absence of systemic hypertension, demonstrating conclusively that NPR1-signaling functions as an intrinsic inhibitor of myocyte growth." (PMID 23372767, 2013). "Interestingly, in knock-out mice lacking the NPR 1 gene coding for NPR-A, not only high ANP concentrations, hypertension and cardiac hypertrophy, but also expression of pro-inflammatory markers are observed." (PMID 31830996, 2019).
Hypertension (32 papers, 2009 to 2026). The presence of chronic increased pressure in the systemic arterial system. "Genetic studies have demonstrated the association of polymorphisms and allelic variants of ANP (Nppa), BNP (Nppb), and GC‐A/NPRA (Npr1) with a family history of hypertension, increased left ventricular mass, and cardiovascular diseases (CVD) in humans." (PMID 39109516, 2024). "Nitroprusside, which is a powerful vasodilator used to treat hypertension, is an agonist for Npr1, a gene implicated in vascular aging in mice." (PMID 37450404, 2023). "The previous clinical and genetic studies strongly support our present findings that a positive association exists between the polymorphisms of Nppa, pro-BNP (Nppb), and Npr1, causing essential hypertension, increased cardiac mass, and CVD." (PMID 36232788, 2022). "Several studies have demonstrated a link of ANP (NPPA), BNP (NPPB), and NPRA (NPR1) polymorphisms with hypertension and CVDs in humans." (PMID 34489721, 2021). "It has been reported that a positive association exists between the polymorphisms of NPPA, NPPB, and NPR1 causing essential hypertension and LHV." (PMID 34489721, 2021). "CG31183 is predicted to be involved in protein phosphorylation and intracellular signal transduction and its human homolog, NPR1, has been implicated in hypertension and cardiovascular disease." (PMID 22496853, 2012). "Deletion of Npr1 (NPR-A) in mice leads to hypertension, hypertrophy, and cardiac fibrosis, whereas genetic ablation of Npr2 (NPR-B) results in dwarfism and female sterility." (PMID 38891063, 2024). "Our previous studies and works from others have shown that systemic targeted disruption of the Npr1 provokes hypertension and cardiac dysfunction in null mutant (0‐copy) and haplotype (1‐copy) mice." (PMID 39109516, 2024). "Another study found that at 12 weeks of age, NPR1−/− mice exhibited worsening cardiac function, characterized by hypertension-related left ventricular hypertrophy and impaired cardiac systolic and diastolic functions." (PMID 38026943, 2023). "The global targeted disruption of the natriuretic peptide receptor-A (NPRA) gene (Npr1) in mice provokes hypertension and cardiovascular dysfunction." (PMID 36232788, 2022). "This review focuses on the intriguing phenotypes of Npr1 gene disruption and gene duplication in mice, with emphasis on hypertension and cardiovascular events using mouse models carrying Npr1 gene knockout and/or gene duplication." (PMID 31416126, 2019). "The resultant Npr1 gene-knockout phenotypes in mice reflect the critical roles of NPRA in physiological and pathophysiological processes occurring in hypertension and cardiovascular disorders." (PMID 31416126, 2019). "Moreover, ablation of Npr1 has indicated that the BP of homozygous mutant mice (0-copy) remains elevated and largely unchanged in response to either minimal- or high-salt diet, suggesting that mutations in Npr1 may also explain salt-resistant form of hypertension." (PMID 31416126, 2019). "Understanding the mechanisms underlying sex‐specific differences in the epigenetic regulation of high BP and renal dysfunction involving Npr1 may reveal new direction to study hypertension and related diseases." (PMID 39109516, 2024). "The current findings suggest that ANG II-mediated repressive mechanisms of Npr1 transcription and receptor function may provide new molecular targets for treatment and prevention of hypertension and cardiovascular diseases." (PMID 32152395, 2020). "The genetic association between the microsatellite marker in Npr1 promoter and left ventricular hypertrophy indicated that the ANP-BNP/NPRA signaling system contributes to cardiac remodeling and congestive heart failure in patients with essential hypertension." (PMID 31416126, 2019).
Hypertension (continued). "We performed BP and renal functional studies in mice with podocyte-specific Npr1 disruption and challenged both sexes with low-salt (LS) and high-salt (HS) diets to determine whether a podocyte-specific inactivation of Npr1 alters hypertension and renal dysfunction in a sex-dependent manner." (PMID 39101921, 2024). "Thus, NPRA may differentially regulate adrenal versus renal renin and Ang II levels, resulting in increased absorption of salt and water through the kidneys, which is critical for the development of hypertension and cardiac dysfunction in Npr1 null mutant mice." (PMID 31416126, 2019). "Interestingly, CM-specific deletion of Npr1 does not impact heart weight and CM cell number, indicating that cardiac hyperplasia is potentially a secondary response to systemic alterations such as arterial hypertension during fetal and neonatal stages." (PMID 38891063, 2024). "Importantly, male mice with the genetic disruption of Npr1 are subject to both hypertension and sudden death due to CHF after they reach six months of age, whereas female Npr1 mice exhibit slightly lower degrees of hypertension but do not suffer sudden CHF and death at adult age." (PMID 36232788, 2022).
gastric cancer (14 papers, 2013 to 2026). A primary or metastatic malignant neoplasm involving the stomach. "Taken together, these findings elucidate the NPR1-driven metabolic mechanism underlying gastric cancer metastasis and suggest NPR1 as a promising therapeutic target for patients with metastatic gastric cancer." (PMID 40539884, 2025). "Here, it is identified that the transmembrane guanylate cyclase, natriuretic peptide receptor 1 (NPR1), promoted gastric cancer lymph node metastasis by activating lipid droplet lipolysis and enhancing mitochondrial oxidative phosphorylation (OXPHOS)." (PMID 40539884, 2025). "Furthermore, targeted delivery of NPR1 siRNA using engineered exosome mimetics effectively suppressed gastric cancer metastasis." (PMID 40539884, 2025). "Similarly, NPR1 interacts with PARL, stabilizing it and contributing to cisplatin resistance in gastric cancer cells." (PMID 40630134, 2025). "Functionally, NPR1 induced lipolysis of stored lipid droplets, releasing bioavailable fatty acids that are imported into mitochondria to upregulate OXPHOS, thus fueling the energy required for the metastasis of gastric cancer cells." (PMID 40539884, 2025).
heart failure (12 papers, 2014 to 2026). Inability of the heart to pump blood at an adequate rate to meet tissue metabolic requirements. "Here we assess XXB750, a human monoclonal antibody activating natriuretic peptide receptor 1, in patients with heart failure." (PMID 41912806, 2026). "The NPR1 signaling pathway plays a pivotal role in cardiovascular diseases such as atrial fibrosis and heart failure, and its attenuation in AF is strongly correlated with remodeling of cardiac structure and function." (PMID 40894480, 2025). "Because common variants associated with BP and heart failure have not yet been fully identified, further studies are needed to characterize the most functionally significant markers of Nppa, Nppb, and Npr1 variants in a large patient population." (PMID 31416126, 2019).
viral infection (10 papers, 2011 to 2025). "However, constitutive expression of NPR1 also rendered plants susceptible to viral infection and hypersensitive to abiotic stresses (salt and drought) in rice." (PMID 20955180, 2011). "Following viral infection, the expression levels of NPR1, PR-1b, PR3, and PR5 genes gradually increased over time in the leaves of N. benthamiana treated with HN-2." (PMID 39049860, 2024). "However, BSG KO and NPR1 KO kidney organoids clearly supported viral infection as demonstrated by confocal microscopy and TEM analysis, thus excluding an essential role of BSG or NRP1 in renal SARS-CoV-2 infections." (PMID 35561674, 2022). "However, PR1 is not believed to possess antiviral activity and SA (salicylic acid)-mediated responses to incompatible virus infection are almost activated by NPR1-independent pathways." (PMID 33198167, 2020). "Similarly, in N. tabacum, it was reported that NtTTG2, containing the WD40 protein interaction domain, inhibits the nuclear localization of the protein NPR1 and the SA/NPR1-regulated defensive responses in plants, hence reducing the resistance to bacterial and viral infections." (PMID 39852478, 2025). "On the other hand, the NPR1 levels in plants inoculated with GBNV alone consistently declined, signifying a higher virus infection compared to the treated plants." (PMID 40104030, 2025). "Pathogenesis-related proteins are central, salicylic acid-mediated plant defense factors that are over-expressed in response to viral infections through the control of non-expresser of PR genes 1 (NPR1; locus AT1G64280)." (PMID 34181647, 2021). "Earlier, disease resistant pathway similar to the Arabidopsis NPR1 (AtNPR1), which also showed negative effects on viral infections, showed negative regulation of this gene in plants under salt and drought stress response." (PMID 27446153, 2016).